MMP8 (matrix metallopeptidase 8)
Diseases named in the same sentence as MMP8 in open-access papers (continued):
Sharing a sentence is not in itself a finding about the gene and the disease.
tumor (continued). "Consequently, our results showed that the nomogram based on direct lung injury, shock, tumor, BPI, MME and MMP8, had incremental predictive value compared to that of the single indicators." (PMID 36685531, 2022). "Immunopositivity for MMP-8 occurred in the tumour cell cytoplasm with mild nonspecific background staining of the extracellular space in some of the samples." (PMID 35328734, 2022). "Tumour MMP-8 expression and a low CRP level may predict a favourable outcome in PDAC with similar results for MMP-8-positive PMNs and low CRP levels." (PMID 35328734, 2022). "Tumour samples from 141 PDAC patients undergoing surgery in 2002–2011 at the Department of Surgery, Helsinki University Hospital were stained immunohistochemically, for which we evaluated MMP-8 expression in cancer cells and the amount of MMP-8-positive PMNs." (PMID 35328734, 2022). "Neutrophils can release neutrophil elastase, matrix metalloprotease 8 (MMP8), matrix metalloprotease 9 (MMP9), vascular endothelial growth factor (VEGF), cathepsin G and proteinase-3 to degrade the extracellular matrix (ECM) and promote tumor invasion." (PMID 33526991, 2021). "Tumoural FXYD5 expression is reported to inversely correlate with E-cadherin expression in many cancers, however we found only minimal decrease in the level of E-cadherin in MMP8 + HSC3 cells compared to control cells." (PMID 34059618, 2021). "Although few immune-related genes had a high expression in cold tumor, such as MMP8, most genes highly express in cold tumor are not so closely related to immune responses, including CGA, INHA, IBSP, and CHRNA9." (PMID 33816503, 2021). "Indeed, MDSCs produce high levels of MMPs, including MMP2, MMP8, MMP9, MMP13, and MMP14, which by digesting ECM allow tumor cells migration." (PMID 32133298, 2020). "Some studies have reported that Ephrin reverse signaling could promote EMT and invasion in a variety of tumor cells by activating Src, STAT3, MMP8 (matrix metalloproteinase 8), and RAC1." (PMID 31893311, 2020). "To sum up, we speculate that MMP8, MMP11, TFDP3, F2, and CNTN1 can promote the progression of GAC while MYB could be a tumor suppressor in GAC." (PMID 32309437, 2020). "Additionally, these neutrophils were shown to secrete increased amounts of MMP8 and MMP9, which facilitated tumor cell extravasation and metastasis." (PMID 31514474, 2019). "Further analysis showed that high MMP8 levels in plasma correlated with tumor stage IV and showed a trend (statistically not significant) towards favorable outcomes." (PMID 31514474, 2019). "Serum MMP-8 is associated with adverse CSS in CRC, independent of tumour stage, grade, lymphatic invasion, BRAF VE1 immunohistochemistry, MMR deficiency, Immunoscore and mGPS." (PMID 29808017, 2018). "Serum MMP-8 showed negative correlation with tumour-infiltrating mast cells (IM: tumour stage, patient age and patient gender adjusted p = 0.005; tumour centre: tumour stage, patient age and patient gender adjusted p = 0.010)." (PMID 29808017, 2018). "From SOM to EOT, e.g. during tumor progression on single bevacizumab treatment, weak evidence was observed for increase in the level of five proteins (TIMP-4, MMP-8, EGF, Amphiregulin, and Tissue factor/Coagulation factor III), whereas a decrease was seen in only one protein (CD26)." (PMID 30592740, 2018). "Since MMP-8 impacts on MEC adhesion and HD formation, we sought to analyse whether altered MMP-8 expression by MEC influences their tumour-suppressor activity." (PMID 28330493, 2017). "TANs recruited by tumor then release pro-growth and pro-invasion factors including hepatocyte growth factor (HGF), reactive oxygen species (ROS), reactive nitrogen species (RNS), neutrophil elastase (NE), neutrophil collagenase (MMP8), and gelatinase B (MMP9)." (PMID 28223716, 2017).
tumor (continued). "MMP-8 and MMP-13 are classified as collagenases because they mainly degrade collagen; MMP-13 is able to degrade the components of the basal membrane and is involved in tumor dissemination and progression." (PMID 27782083, 2016). "Despite the established pro‐tumorigenic roles of certain MMPs (e.g., MMP2, MMP9, and MT1‐MMP), recent studies have demonstrated that some MMPs such as MMP8 and MMP11 might act against tumor growth and metastasis." (PMID 27292876, 2016). "The reduction in MMP-3 expression may itself contribute to the enhanced tumor and metastatic capability of MMTV-PyMT tumors in the Mmp8-null background." (PMID 25848906, 2015). "The associations of MMP-8 with gender, oestrogen receptor levels (separately in cancer cells and in inflammatory cells), tumour thickness, TNM stage, and tumour grading were not statistically significant." (PMID 18253113, 2008). "Overall, this phenotype is reversed following transplantation of wild type bone marrow, confirming that the absence of MMP-8 produced by PMNs and not a tissue or tumour source resulted in the higher incidence of tumors." (PMID 17375198, 2007). "Indeed, at the tumor stromal interface an abnormal inflammatory response is observed, characterised by an initially delayed and then a more diffuse PMN influx in the Mmp8-null mice." (PMID 17375198, 2007). "Furthermore, we opted not to include tumor patients in our prospective cohort since MMP-8 expression levels vary considerably across different types of tumours." (PMID 37464428, 2023). "There were no changes between IDC stratified by tumor size high MMP ratios were also associated with shorter relapse-free survival in patients with DCIS (p-value < 0.001) considering both 3’MMPs/5’MMPs and MMP1/MMP8 ratios." (PMID 38017545, 2023). "Not all studies state where the analyzed MMP8 staining is localized (tumor cells, neutrophils, tumor stroma, etc.), which might partly explain the inconsistency." (PMID 31514474, 2019). "On the other hand, regardless of the active role of various MMPs in tumor progression, matrix metalloproteinase-8 (MMP-8) may have antitumor activity." (PMID 31240326, 2019). "MMP-8 may modulate tumor cell adhesion and invasion by processing non-matrix bioactive inflammatory mediators." (PMID 31240326, 2019). "However, the expression of MMP8 and MMP9 can also be detected in tumor cells in patients with PDAC." (PMID 29515771, 2018). "The patients with high-serum MMP-8 levels (>100 ng/mL) had poor cancer-specific survival, independent of tumour stage, grade, lymphatic invasion, patient age, BRAF VE1 immunohistochemistry, mismatch repair deficiency, Immunoscore and mGPS (multivariate HR 2.12, 95% CI 1.21–3.71, p = 0.009)." (PMID 29808017, 2018). "Since the gMDSCs derived from metastatic 4T1 tumour-bearing animals were able to suppress the EMT-related genes and also induce distinct set of genes; S100A9, MMP8, S100A8, WFDC21, LYZ2, FPR1, CCL3, TGFb2, we reasoned whether these genes could be specific for metastatic/aggressive behaviour." (PMID 28382931, 2017). "However, tumor cell-expressed MMP-8 is also suppressive, so it is likely that the presence of MMP-8 in the tumor microenvironment, rather than its source, is the critical factor." (PMID 25848906, 2015). "Also, the fact that some MMPs (such as MMP-8) produced some anti-tumour properties was not put into consideration in some of these previous treatments." (PMID 26155333, 2015). "However, the absence of MMP-8 led to persistence of neutrophils in MMTV-PyMT lesions at the later stages (10 weeks) of tumor development." (PMID 25848906, 2015). "Interestingly, the arazyme-specific immunoglobulins cross-react with MMP-8 expressed in B16F10-Nex2 cells, and may interfere with tumor cell development in vivo." (PMID 24788523, 2014). "Thus, our results support the data from Montel and coworkers in the observation that MMP8 overexpression in the tumour protects against lymph node metastasis but not against distant metastasis." (PMID 18366705, 2008).
tumor (continued). "Thus, the absence of MMP-8 has multiple consequences for angiogenesis, innate immune responses and metastasis that conspire to promote tumor growth and malignancy, and which may involve systemic disturbance of the protease web." (PMID 25848906, 2015). "ALDH1A3 also upregulated MMP1 and MMP8; however, these were not highly co‐expressed with ALDH1A3 in the patient tumour data." (PMID 37753740, 2024). "Although MMP‐1, MMP‐8, and MMP‐13 exhibit the ability to degrade native fibrillar type I and type III collagen, recent studies have revealed that in UV‐mediated skin collagen damage, there is no significant disparity between the roles of MMP‐8 and MMP‐1." (PMID 39230065, 2024). "We show here that in the absence of MMP-8, the oncogenic program in MMTV-PyMT mice is further accelerated as tumor latency is decreased and the resulting lesions grow larger, generating increased numbers of lung macrometastases." (PMID 25848906, 2015). "To predict and validate the interactions of YKL-40 in the tumor microenvironment, we analyzed mRNA expression of YKL-40, IL-17A, PD-L1, and MMP-8 in 136 samples of CRC tissue and non-cancerous colonic tissue obtained from Gene Expression Omnibus (GEO) datasets GDS4382, GDS4513, and GDS4515." (PMID 37185706, 2023). "Thus, the ratio between MMP1 and MMP8 is decreased after IE8 disruption, resembling the profile observed in healthy breast samples as opposed to tumor samples." (PMID 38017545, 2023). "This indicates that the TAN may not matter, while the MMP-8 activity does, suggesting that MMP-8 may have a favourable effect on survival and act locally as a tumour suppressor." (PMID 35328734, 2022). "Thus, it was proposed that MMP-8 is a tumor protective factor, but as far as we know, there is no report of the action of TCF21 in regulating MMP-8 expression." (PMID 35201460, 2021). "However, the densities of tumour infiltrating CD3+, CD8+, FoxP3+ T cells, CD68+ macrophages and neutrophils did not significantly correlate with serum MMP-8 levels, when the correlations were adjusted for tumour stage, patient age and patient gender." (PMID 29808017, 2018). "Further, levels of related MMPs including MMP1, MMP8, MMP14, MMP2 and MMP9 which have previously been shown to affect tumor cell invasion were not evaluated in these studies and could compensate for MMP13 levels." (PMID 25880591, 2015).
cancer (99 papers, 1995 to 2026). A tumor composed of atypical neoplastic, often pleomorphic cells that invade other tissues. "Discrepant results for the association between the MMP-8 rs11225395 polymorphism and cancer risk have been reported." (PMID 31590330, 2019). "In this study, insignificant results were obtained for the impact of the MMP-8 rs11225395 polymorphism on cancer susceptibility for the overall population." (PMID 31590330, 2019). "Our results of this meta-analysis evaluating the relationship between the MMP-8 rs11225395 polymorphism and cancer risk are reassuring, and suggest that this polymorphism is associated with elevated susceptibility to cancer in non-Asian populations." (PMID 31590330, 2019). "The current epidemiologic literature was systematically summarized to quantitatively assess the genetic impact of the MMP-8 rs11225395 polymorphism on cancer risk." (PMID 31590330, 2019). "Several studies have focused on the relationship between MMP-8 variants and cancer risk, but they have been unsuccessful in drawing reliable conclusions." (PMID 31638929, 2019). "There were 4372 cancer patients and 5066 control participants for the analysis of MMP-8 C-799 T variant." (PMID 31638929, 2019). "A number of studies have evaluated the association of MMP8 genetic variants including C-799 T (rs11225395 C/T), Lys460Thr (rs35866072 A/C), and Lys87Glu (rs1940475 G/A) SNPs, with cancer risk." (PMID 31638929, 2019). "This meta-analysis aimed to systematically review the evidence on cancer risk of the MMP-8 rs11225395 promoter polymorphism." (PMID 31590330, 2019). "Based on the crucial roles of the MMP-8 gene and the prognostic impact of this polymorphism, it is imperative to determine the association between the rs11225395 polymorphism and cancer risk." (PMID 31590330, 2019). "We employed odds ratio (OR) together with 95% confidence interval (CI) to assess the correlation between MMP-8 C-799 T, Lys460Thr, and Lys87Glu polymorphisms and cancer risk." (PMID 31638929, 2019). "Five articles were acquired for assessing the association of MMP-8 Lys460Thr variant on cancer susceptibility, including 3019 cases and 3544 control subjects." (PMID 31638929, 2019). "In contrast to other MMPs that in general are associated with promoting cancer invasion and metastasis, MMP-8 has been associated with a favorable outcome in various cancers." (PMID 31240326, 2019). "We further employed in silico tools to evaluate the effect of MMP-8 expression on cancer susceptibility and overall survival time." (PMID 31638929, 2019). "Several of the genes, such as Mmp8, Dock10, Hoxd3 and Fat3, have previously been reported to show mutation or altered expression in cancer and particularly metastasis." (PMID 28577549, 2017). "Human correlation studies have shown that positive MMP-8 expression is linked to a lower risk of cancer incidence and metastasis, and to prolonged disease-free and overall survival." (PMID 25848906, 2015). "In our experiments, serial passage of transfected breast MDA-MB-231 carcinoma cells expressing WT MMP-8 led, over time, to a progressive loss of expression of the protease." (PMID 23632023, 2013). "Further histopathological studies demonstrated that sustained inflammation resulting from MMP8-deficiency creates a permissive environment for cancer progression." (PMID 22822400, 2012). "It appears that human melanomas are frequently associated with mutations in Mmp8 and Mmp27 genes leading to loss-of-function and enhanced progression of the cancer." (PMID 22822400, 2012). "MMP8 is known to be expressed in various cancer types and may be associated with cancer cell invasion, proliferation, metastasis, and the poor prognosis of cancer patients." (PMID 38031100, 2023). "It is hypothesized that different variants in the promoter region of MMP8 may also influence cancer risk and prognosis." (PMID 36009438, 2022).
cancer (continued). "MMP8 encodes a member of the Matrix metalloproteinases (MMPs), a family of proteolytic enzymes which is involved in degrading components of the extracellular matrix and promoting invasion and metastasis in various cancers." (PMID 34830910, 2021). "Therefore, it is reasonable to summarize all eligible data and draw more accurate conclusions to evaluate the contribution of MMP-8 polymorphisms to cancer risk." (PMID 31638929, 2019). "Furthermore, we employed the TCGA database and Polyphen2 bioinformatics tools to assess the role of MMP-8 expression on cancer risk and survival time." (PMID 31638929, 2019). "Therefore, we conducted a comprehensive analysis based on accumulated data of all eligible studies to investigate the impact of MMP-8 C-799 T, Lys460Thr, and Lys87Glu polymorphisms on overall cancer susceptibility." (PMID 31638929, 2019). "Moreover, our data indicate that MMP8 overexpression may even have an adverse influence on distant metastasis and may predispose cancer cells to spread by the haematogenous route." (PMID 18366705, 2008). "MMP-8 and the MMP-8/TIMP-1 ratio showed weaker associations with incident cancer and cancer mortality only in the 45-54-year age group." (PMID 42162053, 2026). "Among the 22 investigated MMPs, seven genes (MMP2, MMP3, MMP10, MMP12, MMP14, MMP15, and MMP16) were upregulated in cancer, while MMP8 was downregulated." (PMID 41728806, 2026). "We investigated the associations of serum MMP-8, TIMP-1, and the MMP-8/TIMP-1 ratio with prevalent and incident cancer in 8448 individuals aged 25-74 years from the FINRISK97 cohort." (PMID 42162053, 2026). "Another study suggested that MMP8 plays dual roles by promoting or suppressing cancer progression depending on the type of cancer." (PMID 40566630, 2025). "MMP-8 and TIMP-1 have prognostic significance in several cancers, but it has also been reported that MMP-8 has distinct roles in different cancers." (PMID 39917664, 2024). "The clinical significance of MMP8/9 was further analyzed in TCGA datasets, revealing significant correlations between expression levels, neutrophil infiltration and cancer survival in AML and other tumors." (PMID 38730491, 2024). "In the same study, it was found that the more advanced the cancer was, the higher the MMP-8 concentration." (PMID 39917664, 2024). "In clinically annotated TCGA databases, MMP8 was shown to act as an independent indicator for poor prognosis and correlated with higher neutrophil infiltration and poor pan-cancer prognosis." (PMID 38730491, 2024). "The role of MMP8 in cancer is more controversial since its expression has been associated with both better and worse prognoses depending on the tissue of origin." (PMID 38017545, 2023). "This variation in the role of IL-17F in different cancers is common also in other proteins such as MMP-8." (PMID 35012470, 2022). "MMP-8 takes part in tissue remodelling both in inflammation and cancer since it can act as a modulator of the immune response as well." (PMID 35328734, 2022). "The exosome-activated mCAFs upregulate the activity of genes for MMP-1, MMP-2, MMP-7, MMP-8, MMP-13 and MMP-14 that are associated with cancer growth and progression." (PMID 34837514, 2022). "The multivariable analysis confirmed that the MMP-8 expression level in cancer cells represents an independent positive prognostic factor (HR = 0.33; 95% CI 0.16–0.68; p = 0.003)." (PMID 35328734, 2022). "Our results not only demonstrate the role of tissue MMP-8 expression in cancer cells as a positive prognostic factor in PDAC, but also offer a possible protective mechanism through the prevention of chronic inflammation." (PMID 35328734, 2022). "MMP-8 reduces the invasive capacity of cancer and enhances the immune response by regulating neutrophil recruitment, as illustrated in animal and in vitro studies." (PMID 35328734, 2022).